Y_RNA (Y RNA )
Gene: Miscellaneous RNA gene on chromosome 21 (23,432,181 to 23,432,282, reverse strand). Ensembl gene ENSG00000199698.
Homologues: Orthologues: chimpanzee Y_RNA (98% identical). Paralogues in human: Y_RNA (85% identical), RNY3P1 (84% identical), Y_RNA (84% identical), RNY3 (83% identical), Y_RNA (83% identical), Y_RNA (82% identical), RNY3P11 (81% identical), Y_RNA (81% identical), RNY3P14 (80% identical), Y_RNA (80% identical), RNY3P16 (79% identical), Y_RNA (79% identical), and 95 more.